CCL18 (C-C motif chemokine ligand 18)
Diseases named in the same sentence as CCL18 in open-access papers (continued):
Sharing a sentence is not in itself a finding about the gene and the disease.
tumor (continued). "We found that CXCL9+ cells produced CCL18, a strong lymphocyte attractant, suggesting that CXCL9+ cells attract lymphocytes to the tumour vicinity." (PMID 40670667, 2025). "CC-chemokine ligand (CCL) 2, CCL5, and CCL18 and transforming growth factor beta (TGFB) 1 secreted by tumor cells have been described to have chemotactic effects on macrophages." (PMID 39272860, 2024). "These activated macrophages, in turn, secrete CCL-18 and TGF-β1, which drive epithelial-to-mesenchymal transition (EMT) and tumor progression." (PMID 39451551, 2024). "CCL18 can induce proliferation, invasion, and epithelial-to-mesenchymal transition (EMT) in various tumor cells." (PMID 38365809, 2024). "One of the receptors for CCL18 is PITPNM3, which has been extensively studied in the context of CCL18‐dependent migration induction, invasion, and EMT in tumour cells." (PMID 38520216, 2024). "Among them, Macro-2 seems to be a key player in the tumor metastatic cascade, characterized by expression of SPP1, CCL18, CXCL5, CCL2, and CCL7." (PMID 38281962, 2024). "The study found that macrophages within tumor matrices displayed an M2-like anti-inflammatory phenotype, characterized by higher expression of IL-10, TGF-β, and CCL18, and lower expression of CCR7 and TNF." (PMID 38221607, 2024). "The mRNA levels of the cytokines CCL5, CCL18, and GDF15, as well as the transcription factor IRF4, showed a positive correlation with the tumor volume." (PMID 39272860, 2024). "Correlation analysis verified a positive association between MTHFD1 expression and CCL18+ immunosuppressive macrophages, collectively indicating that increased level of MTHFD1 may be associated with the polarization and immunosuppressive functions of macrophage in the tumor microenvironment." (PMID 38730286, 2024). "The mRNA levels of CCL18 and GDF15 were positively correlated with tumor volume in the tumor samples, and the other cytokines were also expressed in the tumor samples." (PMID 39272860, 2024). "TAM secretes pro-angiogenic and tumor-inducing chemokines such as TGF-β, IL‐10, CCL18, matrix metalloproteases, epidermal growth factors and TGF- β." (PMID 38720340, 2024). "The mRNA levels of the cytokines CCL5, CCL18, and GDF15, as well as the transcription factor IRF4, correlated weakly positively with the tumor volume." (PMID 39272860, 2024). "In terms of upregulated DEGs, seven genes (ABI3BP, CTSG, DPP4, CCL18, OSR2, GRIA3, MMP2) demonstrated reduced expression in tumor compared to normal tissue." (PMID 39062832, 2024). "Meanwhile, macrophages can promote tumor invasion and metastasis through secretion of various cytokines (e.g., TGF-β, IL-10, arginase 1) and chemokines (e.g., CCL5, CCL17, CCL18, CCL22)." (PMID 38637499, 2024). "CTNNB1 is a component of the Wnt signaling pathway, which regulates tumor growth and metastasis through the expression of ICAM-1, VCAM-1, CXCR4, and CCL18." (PMID 37190141, 2023). "Here we found that CCL18 was elevated in tumor tissues of ESCC, negatively correlated with the patient survival, and positively correlated with tumor developing stage, which corresponded with its high expression level on TAMs infiltration." (PMID 36850011, 2023). "As a receptor for CCL18, PITPNM3 highly expressed on epithelial and tumor cells in scRNA-seq data and indicated poor prognosis in microarray cohort." (PMID 36850011, 2023). "CCL18+ macrophages with high expression of CD163, MARCO, and CSF1R also exhibited stronger tumor-promoting effects than SPP1+ macrophages." (PMID 38347955, 2023). "Collectively, these data suggested that CD10+GPR77+ fibroblasts induced by CCL18 generate a niche for CSC enrichment, leading to the chemoresistance of tumor cells in vivo." (PMID 36418470, 2023). "The possible mechanisms by which M2 polarization promotes tumor progression and regulates TME involve secretion of growth factors and cytokines, such as IL6 and CCL18." (PMID 36334221, 2023).
tumor (continued). "Subsequently, we analyzed the correlations of CCL18 expression levels with selected clinicopathological features of ESCC patients and found that CCL18 was significantly correlated with tumor stage (P = 0.0001)." (PMID 36850011, 2023). "IL-6 also activates human CD14+ peripheral blood nuclear cells through the STAT3 pathway producing CCL18 and TGFβ, which leads to the induction of the EMT with tumor-promoting effects." (PMID 37190141, 2023). "For BCC, studies have revealed the presence of high concentration of T-regs, not only in TME, but also in the tumor bordering skin, chemoattracted by different chemokines, for example CC chemokine ligand 17, 18 and 21 (CCL17, CCL18 e CCL21)." (PMID 35775005, 2022). "Their study reported the use of CCR5 inhibitor and CCL18 monoclonal antibody to double‐block the CCL5‐CCR5 and CCL18‐PIPTNM3 pathways, which led to significant suppression of tumor metastasis." (PMID 34914196, 2022). "We measured the expression of CCL18, CCR8 and PITPNM3 in the GMB tumor from patients (16 men and 12 women) using quantitative real-time polymerase chain reaction." (PMID 35955670, 2022). "In contrast, CCL18+ macrophages showed a dominant M2-like phenotype with the high expression of CD163, MARCO, and CSF1R, suggesting their stronger tumor-promoting role than SPP1+ macrophages." (PMID 35347134, 2022). "Ligand-receptor interaction analyses indicated extensive cross-talk between the metastatic tumor cells and the MRC1+/CCL18+ macrophages; an example is the “don’t-eat-me” signaling between CD47 on tumor cells and SIRPA on the macrophages." (PMID 36376874, 2022). "A heatmap profiles showed that CTSK, MMP9, CKB, CCL18 and COL6A2 were upregulated in macrophages in tumor tissues." (PMID 36466840, 2022). "In the present study, we focus on the role of the chemokine CCL18 and its receptors in the GBM tumor." (PMID 35955670, 2022). "We observed that the OSCC secretome induced CCL18 gene expression in Teff and CCL18 was able to promote CCR8 expression, therefore it would be interesting to observe how the tumor environment is able to regulate this chemokine to promote CCR8+ cells." (PMID 34025655, 2021). "Once in the tumor, TAMs secrete pro-angiogenic factors such as VEGF-A, TGF-β, fibroblast growth factor-2 (FGF-2), CCL18, semaphorin 4D (Sema4D), adrenomedullin (ADM), and placental growth factor (PlGF)." (PMID 33783686, 2021). "Some M1 markers (IL1A, IL1B, CD86), M2 markers (CCL18, MRC1/CD206, CSF1R), and TAM markers (HLA-DR, IL1RN, CD163, ITGAM, SIGLEC1/CD169) were highly expressed on both tumor and non-tumor macrophages." (PMID 33918618, 2021). "M2 TAMS drive tumor cell EMT via GM-CSF and CCL18 while N2 TANs remodel the ECM of tumor cells via Neutrophil Elastase (NE) and MMP9." (PMID 34830776, 2021). "Besides CAFs, tumor-associated macrophages (TAMs), as myeloid derived suppressor cells, contribute to an immunosuppressive microenvironment and support tumor growth as they are a source of immunosuppressive cytokines (e.g., CCL17, CCL18 and CCL22) and tumor promoting growth factors (VEGF-A, TNF-α)." (PMID 34064974, 2021). "An immune-suppressive tumor environment constituted by Tregs and M2 macrophages along with immunosuppressive mediators such as CCL17, CCL18, CCL22, and PD-L1 can assist tumor development and progression." (PMID 34937192, 2021). "CCL18+M1, CXCL9+M2, and TIMP1+M3 were enriched in tumor tissues and were regarded as TAMs, whereas SELENOP+M4, MMP7+M5, CHIT1+M6, and PPARG+M7 were enriched in normal tissues and considered as resident tissue macrophages (RTMs)." (PMID 34659209, 2021). "In addition, immunofluorescence staining revealed that CCL18 is preferentially expressed by macrophages in the invasion margin of the tumor, suggesting that CCL18 may be one facet in a series of complex, coordinated changes that facilitate malignant dissemination in late-stage disease." (PMID 34204115, 2021).
tumor (continued). "TAMs can produce various chemokines, such as CCL17, CCL18, and CCL22, which attract Treg cells to tumor sites, thereby impeding cytotoxic T cell activation." (PMID 33568167, 2021). "Considering that HMSC-128-EV were able to affect CCL18 expression of BUC T24, we further investigated the effect of HMSC-128-EV on the tumor process." (PMID 35059433, 2021). "TAMs can synthesize chemokine ligand 5 (CCL5), chemokine ligand 8 (CXCL8), and selectively synthesize CCL18, CXCL2 and CXCL3, all of which can attract monocytes/macrophages and promote tumor progression." (PMID 32774171, 2020). "Additionaly, CCL18 is proved to play a crucial role in the migration and EMT processes of tumor cells by activating receptors other than PITPNM3." (PMID 33114763, 2020). "In the current study, we also found that especially four chemokines were upregulated in the recurrent tumor compared to the primary tumor; CCL13, CCL18, CCL19, and CXCL14." (PMID 33352957, 2020). "CCL18 from TAMs promoted tumor cell EMT and functioned as a crucial microenvironmental factor involved tumor progression." (PMID 33424843, 2020). "We also identified two new subsets, including CCL18+ M2 macrophages enriched in advanced HCC, and XCL1+ CD8+ T cells capable of recruiting DC to enhance anti-tumor response." (PMID 33298893, 2020). "CCL18 closely correlated with serum EBV infection titers and tumor progression in two cohorts of NPC patients." (PMID 33424843, 2020). "This receptor has been best studied in CCL18-dependent migration induction, invasion and epithelial-to-mesenchymal transition (EMT) tumor cells." (PMID 33114763, 2020). "The 48 h coculture initiates a pro-tumor phenotype skewing of MΦ, indicated by downregulation of IL1B, IL12, CCL18, CD80, as well as CD163, and upregulation of CLEC7A (dectin-1), CD86, CD206, and HLA-DR." (PMID 30850595, 2019). "HGSOC ascites are a pro-inflammatory tumor environment that contains a variety of cytokines, chemokines and growth factors including leptin, hepatocyte growth factor (HGF), IL-6, and CCL18." (PMID 31039761, 2019). "TAMs exert a pro-tumor effect, inhibiting antitumor activities by secreting chemokines such as CCL17, CCL18 and CCL22, which attract Tregs cells to tumor sites, compromising the immune responses of CD8 + cytotoxic T cells." (PMID 31600917, 2019). "We identified an increased expression of genes that were previously found in the astrocytes from tumor specimens, (HLA-DRA, CHI3L1 SERPINA1, CCL18, CD37, and CD274)." (PMID 31186414, 2019). "Increase of CCL18 released by alternatively activated macrophages in a pro-fibrotic environment might therefore mask this decrease, resulting to “false” stable concentrations due to two different pathomechanisms (CCL18 decrease due to tumor regression and increase due to RILT)." (PMID 28957436, 2017). "Cells in the tumor microenvironment, including both tumor cells and stromal cells, overexpressed chemokines such as CCL2 (MCP-1), CXCL12 (SDF-1), CCL9 (MIP-1γ) and/or CCL18 (PARC), and recruit MOs into the tumor bed." (PMID 26155942, 2015). "The addition of CXCL12 or CCL18 immunoneutralizing antibody in the co-culture system of CAFs and MDA-MB-231 reduced tumor cell invasion by nearly 60%." (PMID 23577100, 2013). "Thus, CCL18 might also be engaged in the formation of the tumor stroma." (PMID 22848587, 2012). "Despite the different tumor biology of squamous and adenocarcinoma there seems to be a concordant course of induction in both histological subtypes and the potency to foster alternative activation of macrophages and subsequently to induce CCL18 release may be a general property of malignant cells." (PMID 22848587, 2012). "In noncancerous tissue, top DEGs included chemokine CCL18 (fold change [FC] = 6.54; FDR = 6.36 × 10−2), which is released by tumor-associated macrophages to promote cancer cell invasion, and coagulation factor F8A3 (FC = 3.18; FDR = 1.36 × 10−4)." (PMID 39951265, 2025).
tumor (continued). "Although increased CD8+ T-cell infiltration was associated with improved survival in our cohort, the concomitant overexpression of CCL18 and epigenetic silencing of MAPK10 indicate a complex interplay between tumor-intrinsic alterations and the immune microenvironment." (PMID 41472741, 2025). "Functionally, SPP1+ TAMs play a central role in promoting tumor cell epithelial-mesenchymal transition (EMT), angiogenesis, intravasation, metastasis, and immunosuppression through the secretion of factors including SPP1, CCL18, CXCL8, TNF-α, and IL-1β." (PMID 41459510, 2025). "CCL18 also stimulates ELMO1 and PI3K/AKT, driving tumour cell motility and reinforcing EMT." (PMID 40361472, 2025). "By integrating gene expression, epigenetic, immune, and survival data, this analysis underscores the central roles of CCL18 and EGF within the tumor ecosystem and highlights the value of network-based approaches in uncovering novel regulatory axes in cancer progression." (PMID 40692603, 2025). "The authors also discovered that metastatic tumor cells tend to express the ligand CD47, an important “don’t-eat-me” signal, which may influence the anti-tumor immunity of MRC1+ CCL18+ macrophages via its corresponding receptor SIRPA." (PMID 40191203, 2025). "Some reports describe that the tumor immune escape can be driven by other immunosuppressive cytokine loops, including CCL22, CCL17, and CCL18 that are also secreted by macrophage for recruiting Treg cells and modulate the immune response during the tumorigenic process." (PMID 39061137, 2024). "Moreover, it is possible that CCL2, CCL5, CCL18, TGFB1, and GDF15 are also produced by cells other than the VS tumor cells." (PMID 39272860, 2024). "Crosstalk between TAM and tumor cells has been confirmed by the positive feedback loop that induces the epithelial–mesenchymal transition (EMT) of tumor cells and secretes GM-CSF and CCL18." (PMID 38520648, 2024). "CCL18 is mainly produced by TAMs in a variety of tumor types, but it plays no role in actually facilitating their initial accumulation." (PMID 38339310, 2024). "Cytokines, including CCL2, CCL5, CCL18, TGFB1, and GDF15, are produced by tumor cells and attract immune cells, such as macrophages and lymphocytes, from the blood and bone marrow into the tumor microenvironment." (PMID 39272860, 2024). "Macrophages could be polarized to the tumor growth-promoting M2 subtype in the tumor environment by cytokines, such as CCL2, CCL5, CCL18, and TGFB1 and the mRNA levels of the transcription factor IRF4." (PMID 39272860, 2024). "Our results might suggest an influence of the immunomodulatory cytokines CCL5, CCL18, GDF15, and TGFB1 on tumor progression." (PMID 39272860, 2024). "CCL5 and CCL18 upregulate various glycolysis-promoting factors, including hexokinase 2 (HK2), phosphoglycerate kinase 1 (PGK1), glucose-6-phosphate dehydrogenase (G6PD), and pyruvate kinase, further facilitating tumor progression." (PMID 38714539, 2024). "Anti-TNFR2 mAb treatment might destroy the chemotactic attraction between CCL18+ macrophages and CCR8+ Tregs, leading to a reduction in tumour-infiltrating CCR8+ Tregs." (PMID 37935468, 2024). "Another study focused on HNSCC revealed that SPP1 + TAMs might enhance tumor intravasation and metastasis via the secretion of SPP1, CCL18, and CXCL8." (PMID 39726047, 2024). "We observed that CCL18 was highly expressed in tumour-infiltrating CD68+ macrophages, which attracted Tregs via the CCL18/CCR8 interaction, so we speculated that CCL18+ macrophages could lead to the accumulation of CCR8+ Tregs in the TME." (PMID 37935468, 2024). "PMs can be switched to tumor-associated macrophages (TAMs) in ascites with pro-tumor effect by releasing various soluble mediators, including IL-6, IL-10, CCL18, CCL22, TNF-α, TGF-β, and EGF that triggers pro-tumorigenic signaling pathways in tumor cells and infiltrating leukocytes in the TME." (PMID 37932814, 2023).
tumor (continued). "Blocking CCL18 by administration of anti-CCL18 neutralizing antibody could inhibit the formation of CD10+GPR77+ CAFs in vivo, and recover the chemosensitivity, leading to effective tumor control." (PMID 36418470, 2023). "Chemokines secreted by TAMs, including CCL3, CCL5, CCL15, CCL18, CXCL8 and CXCL12, promote tumor metastasis, angiogenesis, cancer cell survival, immunosuppression and resistance of cancer cells after chemotherapy via CCR1/5, CCR5, CCR1, CCR8, CXCR1/CXCR2, CXCR4, respectively." (PMID 36173487, 2023). "Blocking CCL18–PITPNM3 signaling could not only impede tumor cell metastasis, reverse immunosuppression, suppress angiogenesis and inhibit tumor progression but also block the evolution of tumor-promoting CAFs in the early stage of tumor progression." (PMID 36418470, 2023). "These infiltrated immune cells and solid tumor cells release tumor-progressing cytokines (IL-6, TNF-α, TGF-β), chemokines (CCL2, CCL5, CCL18, CXCL8, CXCL12), and growth factors (EGF, PGF, IGF-1, IGF-2, PDGF) that promote tumor microenvironment immunosuppressive." (PMID 37371075, 2023). "Similar to our previous results, CCL18, CCL26, and LIGHT had the most dramatic effects in promoting OXTRLow CAFs-induced HN6 invasion, but only knockdown of CCL26, and with a lesser extent of CCL18, impaired OXTRHigh CAFs-dependent tumor invasion." (PMID 36045118, 2022). "S100P + SPP1− iCCAphl had less CD3+ T and CD56+ NK cells, but more CCL18+ macrophage infiltration than S100P-SPP1 + iCCApps, indicating its dampened anti-tumor immune response that may contribute to the higher invasive potential." (PMID 35347134, 2022). "TAMs-related functions are also regulated by several genes, including C-C motif chemokine ligand 2 (CCL2), C-C motif chemokine ligand 18 (CCL18), TANK-binding kinase 1 (TBK1), and IFN regulatory factor 3 (IRF3), whose signaling pathway is activated during tumor angiogenesis." (PMID 36432658, 2022). "Immunofluorescent, Western Blot, and qPCR showed that C8018‐7840 notably decreased CCL18‐PITPNM3 induced vimentin and recovered CDH1 expression, which further confirmed that C8018‐7840 inhibited PITPNM3 dependent tumor metastasis." (PMID 36285700, 2022). "As a result, GPR84, NCF2, HK3, LILRB2, and CCL18 significantly affected the overall survival (OS) of GBM patients (multivatiate Cox p < 0.05), of which the protein level of GPR84 and NCF2 was significantly increased in the tumor core region." (PMID 36177003, 2022). "Mechanisms that mediate this reduced recruitment of Tregs to HNSCC tumor microenvironments following BRB-E administration are still under active investigation, although chemokine-dependent infiltration via Ccl1, Ccl18, and Ccl22, and Vegfa-dependent recruitment are potential mechanisms." (PMID 36016924, 2022). "Inhibition of CCL18 expression can significantly inhibit the proliferation, invasion, and migration of BUC T24, indicating that the high expression of CCL18 plays an important role in the maintenance of UCs tumor process." (PMID 35059433, 2021). "In addition, different kind of chemokines from M2-like macrophages including CCL18 and CCL22 mediate immune cells migration to tumor microenvironment." (PMID 34194433, 2021). "It is suggested that blocking CCL18 by miR-128 may inhibit the EMT of UCs cells, thereby regulating tumor invasion." (PMID 35059433, 2021). "Increased levels of chemokines, CXC11 and CCL18, and VEGFA mRNA levels in cHRPC further confirmed the tumor-supporting role of HRPC towards 92.1UM probably through different molecular strategies, i.e., (i) promoting monocyte chemotaxis and (ii) stimulating angiogenesis." (PMID 32756477, 2020). "Importantly, we detected and validated a new subset of CCL18+ M2 macrophages and a new subset of XCL1+CD8+ T cells that correlated with disease progression and anti-tumor responses, respectively." (PMID 33298893, 2020).